GDF15 (growth differentiation factor 15)
Diseases named in the same sentence as GDF15 in open-access papers (continued):
Sharing a sentence is not in itself a finding about the gene and the disease.
breast carcinoma (continued). "This hypothesis was addressed by the experiments that increasing the expression of either GDF15 or PTGS2 mRNA in breast cancer cells generated same phenotype as IMP1 knockdown." (PMID 26910917, 2016). "However, the predictive value of GDF-15 levels for the risk of cardiotoxicity induced by neoadjuvant dual anti-HER2 therapy has not been reported in HER2-positive breast cancer patients, which is clinically important." (PMID 38828460, 2024). "Thus, this study aimed to investigate the correlation of GDF-15 levels with clinical features, biochemical indices, and especially its predictive value for the risk of cardiotoxicity in HER2-positive breast cancer patients receiving neoadjuvant dual anti-HER2 therapy." (PMID 38828460, 2024). "Elevated expressions of GDF15 and BMP4 were associated with poorer prognosis comparing the low expression cohort (122.64 months) in HER2 negative patients with HER2 positive group (P<0.01), which indicates that GDF15 and BMP4 tend to promote the progression of breast cancer in HER2 (+) patients." (PMID 37333824, 2023). "Likewise, few studies have focused on the levels of systemic GDF-15 in breast cancer patients." (PMID 35677046, 2022). "Therefore, exploring the effect of GDF15 on the radioresistance of breast cancer may open up a new avenue for clinical radiotherapy." (PMID 36142823, 2022). "Although causal association was not determined, BA-derived GDF15 might possibly contribute to the progression of breast cancers." (PMID 32492819, 2020). "However, few studies have examined GDF15 expression, signaling, or function in breast cancer." (PMID 29212236, 2017). "The present study revealed that in HER2-positive breast cancer patients receiving neoadjuvant dual anti-HER2 therapy, the GDF-15 level was greater in patients who experienced cardiotoxicity than in those who did not." (PMID 38828460, 2024). "BMP7, GDF15, BMP5, SMAD6 and FSTL5 were highly expressed in the ER positive breast cancer cells (MCF-7 cells), while the expressions of TGFBR2, FSTL1 and NOG were reduced in this cohort." (PMID 37333824, 2023). "In four main subtypes of breast cancer, elevated expression of BMPR1B and ACVR2B were seen in Luminal A subtype, while BMP4, GDF15 and ACVR1B were higher in Luminal B, TGFBR1 and BMP8A were higher in HER2 positive, BMP2, BMP6 and GDF5 were higher in TNBC." (PMID 37333824, 2023). "Diltiazem administration in vivo also upregulated the serum level of GDF-15, as well as reduced EMT and MMP-9/MMP-2 expression, leading to a decrease in metastasis of breast cancer." (PMID 36831338, 2023). "Taken together, these findings indicate that GDF-15 reverses EMT and inhibit breast cancer motility." (PMID 35963873, 2022). "We have identified the secretion of GDF15 as a response biomarker of eribulin treatment, as well as a specific biomarker of DTP cells in breast cancer." (PMID 35626166, 2022). "Administering recombinant GDF-15 also reverses EMT, inhibits colony formation and migration in breast cancer cells." (PMID 35963873, 2022). "Diltiazem administration in vivo also upregulates serum level of GDF-15, diminishes EMT and MMP-9/MMP-2 expression, leading to the decrease of lung metastasis of breast cancer." (PMID 35963873, 2022). "The finding of increased expression of KIAA1199, GDF15 and KRT81 in our FSCN1CON compared to FSCN1KD TNBC is consistent with its over-expression in this breast cancer subtype and promotion of their migration." (PMID 34959629, 2021). "GDF‐15 levels were 338 ng/L (IQR:205‐534) for the total cohort, and values were comparable for different tumour entities except breast cancer." (PMID 31463975, 2019). "Positive correlations were noted between visfatin, GDF15, and phosphor-AKT expressions in human breast cancer specimens." (PMID 31861872, 2019). "Consistent with the GDF15-driven EMT we observed in our studies, GDF15 was recently shown to maintain stem cell characteristics in breast cancer cell lines." (PMID 29212236, 2017).
breast carcinoma (continued). "In the current study, we provide mechanistic insights into the signaling pathways driving GDF15-mediated EMT and invasion in breast cancer." (PMID 29212236, 2017). "GDF15 promotes the acquisition of cancer stem cell-like properties in breast cancers, and confers resistance to HER2-targeted therapy in breast cancer." (PMID 29212236, 2017). "In the current study, we demonstrate that GDF15 promotes EMT and invasiveness of breast cancers through insulin-like growth factor-1 receptor (IGF-1R) signaling and transcription factor FoxM1 upregulation." (PMID 29212236, 2017). "Human growth factor array demonstrated that VASH2 promoted proliferation in breast cancer cells via the upregulation of FGF2 and growth/differentiation factor-15 (GDF15) expression." (PMID 24920244, 2014). "Similarly, GDF15 (4.49-fold increase), which encodes another member of the TGF-β superfamily, was reported to exert proapoptotic and anti-tumorigenic functions on colorectal, prostate, and breast cancer cells in vitro and on colon and blioblastoma tumors in vivo." (PMID 24161199, 2013). "Of the other listed genes, GDF15, c-Met and the HOX loci have been shown to act as possible oncogenes in breast cancer, squamous cell lung cancer, prostate and pancreatic cancer." (PMID 18442402, 2008). "Moreover, YAP represses GDF15 transcription to promote metastasis of breast cancer cells by recruiting EZH2 and trimethylating histone H3 lysine 27 on the promoter of GDF15." (PMID 38245781, 2024). "BMP2, BMP4, GDF15 and TGFBR1 were significantly correlated with T stage of breast cancer." (PMID 37333824, 2023). "Collectively our findings suggested that vADSCs may mediate breast cancer EMT and stemness via a GDF15-induced AKT pathway, and promote angiogenesis through a GDF15 independent pathway." (PMID 31861872, 2019). "We found that GDF15, but not TGFβ, increased tumor sphere formation in several breast cancer cell lines and patient-derived primary breast cancer cells." (PMID 28206960, 2017). "Because we examined a small number of cases within each subtype of breast cancer, it is possible that the extremely high expression of GDF15 in human breast cancer tissues will be observed regardless of the subtype." (PMID 28206960, 2017). "We found that GDF15 strongly induced tumor sphere formation in the luminal type MCF7, HER2-positive type BT474, and basal type BT20 cells, which are cell lines representative of each subtype of breast cancer." (PMID 28206960, 2017). "Consistent with this concept, stable overexpression of GDF15 conferred spheroid-forming capability to breast cancer cells, in contrast to parental cells, which did not form spheroids in 3-d culture." (PMID 29212236, 2017). "Based on data indicating that GDF15 mediates EMT and invasion, we hypothesized that knockdown of GDF15 expression would block invasiveness of breast cancers that overexpress GDF15." (PMID 29212236, 2017). "Thus, our results support the conclusion that GDF15 should be considered as a possible therapeutic co-target to eradicate or prevent the development of DTP cells during treatment with eribulin in both TNBC and luminal breast cancer subtypes." (PMID 35626166, 2022). "Similar results to the cell line studies were seen when treating breast cancer-derived PDXO with the same combinations, supporting the idea that GDF15 neutralization in combination with drug treatment may hold considerable potential as an effective therapeutic approach for breast cancer." (PMID 35626166, 2022). "Thus, our data in the breast cancer space suggest that GDF15 should be considered as a possible therapeutic co-target to eradicate or prevent the development of DTP cells during treatment with eribulin in both TNBC and luminal breast cancer subtypes." (PMID 35626166, 2022).
breast carcinoma (continued). "GDF15 may be involved in the proliferation, migration, invasion, and angiogenesis of tumors, with with recent research finding GDF15 promoted EMT and invasion of breast cancers, and supported the maintenance of breast cancer stem-like cells." (PMID 31861872, 2019). "To analyze the GDF15-induced signaling pathways involved in tumor sphere formation, we first examined the phosphorylation of Smad2 by western blot analysis to determine whether GDF15 stimulates the Smad pathways in MCF7 breast cancer cells." (PMID 28206960, 2017). "Furthermore, higher levels of BMP2, BMP6 and GDF5 were revealed in triple negative breast cancer (TNBC) whilst BMP4, GDF15, ACVR1B, ACVR2B and BMPR1B were relatively higher in Luminal type BC." (PMID 37333824, 2023). "The receptor for GDF15 has not been identified; however, a potential cross-talk is activated by GDF15, which induced phosphorylation of HER2 and downstream Akt and Erk1/2 in HER2-overexpressing SKBR3 and BT474 breast cancer cells." (PMID 23227361, 2012).
sarcopenia (64 papers, 2017 to 2026). Progressive decline in muscle mass due to aging which results in decreased functional capacity of muscles. "Of these 13 patients, 12 (92.3%) were in the high‐risk GDF‐15 group having both high GDF‐15 and sarcopenia." (PMID 41380167, 2025). "While the direct molecular target of metformin remains undetermined, its effects on the lysosomal AMPK pathway and subsequent effects on GDF15 highlight its potential role in improving muscle health and reducing the risk of sarcopenia." (PMID 40119457, 2025). "This study investigated plasma GDF-15 as a biomarker associated with sarcopenia and frailty in a cohort of mobility-limited older adults." (PMID 41286529, 2025). "Emerging evidence has identified GDF15 as a biomarker closely associated with sarcopenia, as elevated levels correlate with reduced muscle mass, diminished strength, and impaired physical performance in older adults." (PMID 41441428, 2025). "Our findings demonstrate that elevated preoperative serum levels of IL‐6 and GDF‐15 are closely associated with the presence of sarcopenia, adverse pathological features and diminished survival outcomes in patients undergoing RC for BC." (PMID 41380167, 2025). "Another critical biomarker implicated in cancer‐related sarcopenia is growth differentiation factor‐15 (GDF‐15)." (PMID 41380167, 2025). "Both high IL‐6 and GDF‐15 in serum, as well as sarcopenia, are independent and combined risk factors in patients undergoing RC for BC." (PMID 41380167, 2025). "Levels of Growth Differentiation Factor-15 (GDF15), also a TGFβ superfamily member, are positively associated with aging and sarcopenia, but negatively associated with muscle mass, supporting GDF-15 as a potential important biomarker of sarcopenia." (PMID 40772803, 2025). "Receiver operating characteristic (ROC) analysis was performed to assess the diagnostic accuracy of GDF-15 for identifying frailty and sarcopenia." (PMID 41286529, 2025). "Colocalization analysis confirmed that GDF15 shared a common SNP for the risk of sarcopenia traits, which further illuminates possible targets and biological mechanisms for metformin to trigger sarcopenia risk." (PMID 40119457, 2025). "Another large study found that after adjusting for confounders such as age, comorbidity, and malnutrition, GDF-15 remains independently associated with sarcopenia." (PMID 40869206, 2025). "Lower eGFRdiff and elevated GDF‐15 levels are associated with sarcopenia, frailty, CKD progression and mortality." (PMID 40700030, 2025). "Age (< 70 years, p = 0.02), higher ASA score (p < 0.01), neoadjuvant chemotherapy (p = 0.03), and sarcopenia (p = 0.03) were associated with higher levels of GDF‐15." (PMID 41380167, 2025). "Elevated GDF15 levels are associated with frailty, sarcopenia, cardiovascular disease, and metabolic disorders." (PMID 40295347, 2025). "The combination of high GDF‐15 serum levels and the presence of sarcopenia was an independent risk factor for worse OS and CSS." (PMID 41380167, 2025). "The association between elevated GDF‐15 levels and sarcopenia observed in our study is supported by previous research." (PMID 41380167, 2025). "Different risk groups separated by sarcopenia and high GDF‐15 in serum and the distribution of tumour characteristics and survival." (PMID 41380167, 2025). "GDF-15 can be released by muscle cells upon cellular stress and death, as observed in exercise, sarcopenia and mitochondrial myopathy, also associated with regenerating and denervated muscle fibres in idiopathic inflammatory myopathies." (PMID 38058222, 2025). "Although primarily linked to cancer cachexia, recent studies have identified GDF15 as a key regulator of muscle deterioration in conditions like sarcopenia." (PMID 40837873, 2025). "In a secondary analysis of over 1000 patients, elevated GDF-15 was associated with both the presence of frailty as well as sarcopenia." (PMID 40869206, 2025).
sarcopenia (continued). "Drug target Mendelian found that increased GDF15 was associated with a reduced risk of sarcopenia, as well as positively associated with a decrease in adverse events, which was the most significant effect." (PMID 40119457, 2025). "Future research should focus on elucidating the precise molecular mechanisms underlying IL‐6 and GDF‐15‐mediated sarcopenia and evaluating the efficacy of targeted therapies in clinical trials." (PMID 41380167, 2025). "After applying the outcome‐related cutoffs and investigating the association of dichotomized GDF‐15 with sarcopenia and frailty, respectively, GDF‐15 was found to be associated with the outcomes both in the crude models and the final adjusted models." (PMID 38890783, 2024). "Growth differentiation factor 15 (GDF15), a novel biomarker associated with sarcopenia, and its potential as a therapeutic target for muscle wasting in postmenopausal women." (PMID 39640884, 2024). "Nevertheless, the mechanisms by which higher levels of GDF‐15 are associated with sarcopenia and frailty are yet to be elucidated." (PMID 38890783, 2024). "In this study, we investigated the association of GDF‐15 with sarcopenia and frailty in older, acutely admitted medical patients." (PMID 38890783, 2024). "We found strong associations of dichotomized GDF‐15 with frailty and sarcopenia, respectively, highlighting the clinical usability of our established GDF‐15 cut‐offs." (PMID 38890783, 2024). "It has been reported that plasma levels of GDF15 are associated with low muscle function and sarcopenia." (PMID 38808117, 2024). "Another member of the (TGF-β) family that is related to loss of muscle mass due to aging and sarcopenia is growth differentiation factor 15 (GDF15), also known as macrophage inhibitory cytokine 1 (MIC-1)." (PMID 38409184, 2024). "Results regarding the association between GDF‐15 and sarcopenia, demonstrated an Odds Ratio (OR) (95% CI) in the crude model of 2.3 (1.4–3.7), and an adjusted OR (aOR) (95% CI) of 2.0 (1.2–3.3) in the adjusted final model." (PMID 38890783, 2024). "The IC domains composite score was significantly associated with functional ability, perceived health, sarcopenia, and systemic inflammation biomarkers such GDF-15, IL-10, and IL-10/TNF-α ratio in pre-frail older adults." (PMID 38510450, 2024). "We aim to investigate the association of plasma GDF‐15, measured within the first 24 h of an acute admission, with sarcopenia and frailty in older medical patients." (PMID 38890783, 2024). "As a whole, these data suggest that c-GDF15 is associated with decreased muscle strength and mass and can be useful to identify patients with muscle function impairment/sarcopenia, in particular elderly ones." (PMID 38808117, 2024). "The literature regarding the association of GDF‐15 with sarcopenia and frailty in older hospitalized patients is scarce." (PMID 38890783, 2024). "When elevated above the defined cutoffs, GDF‐15 was strongly associated with frailty and sarcopenia in both crude and fully adjusted models." (PMID 38890783, 2024). "As mentioned, an association of the circulating GDF15 (c-GDF15), i.e. the mature GDF15 homodimer, with sarcopenia and muscle atrophy has been suggested." (PMID 38808117, 2024). "When elevated above the derived cutoffs, GDF‐15 was strongly associated with frailty and sarcopenia in both crude and fully adjusted models." (PMID 38890783, 2024). "We investigated the association of plasma GDF‐15 with sarcopenia and frailty in older, acutely admitted medical patients." (PMID 38890783, 2024). "Previous studies have shown that pro-inflammatory biomarkers, including IL-6, IL-10, IL-8, IL-15, CRP, TNF-α, and GDF-15, are associated with skeletal muscle decline and sarcopenia." (PMID 38026977, 2023). "Cross-sectional and 2 year prospective analyses involving 788 participants supported the finding that an increased level of GDF-15 was associated with the prevalent sarcopenia." (PMID 37577356, 2023).